SNX7 (sorting nexin 7)
Description:
Involved in the regulation of endocytosis and in several stages of intracellular trafficking. Together with SNX4, involved in autophagosome assembly by regulating trafficking and recycling of phospholipid scramblase ATG9A.
Tractability: Small molecule: it has a binding pocket of medium quality. Antibody: UniProt places it where antibodies can reach, with medium confidence. PROTAC: ubiquitination databases record sites on it; its protein half-life has been measured.
Gene: Protein-coding gene on chromosome 1 (98,661,672 to 98,760,504, forward strand). Ensembl gene ENSG00000162627.
Subcellular location: Early endosome membrane
Subcellular location (Human Protein Atlas): Vesicles; Cell Junctions
Gene Ontology:
Molecular function: protein binding; phosphatidylinositol binding
Biological process: positive regulation of autophagosome assembly; protein transport; endocytic recycling; mitophagy; piecemeal microautophagy of the nucleus; reticulophagy
Cellular component: early endosome; early endosome membrane; phagophore assembly site; cytoplasmic vesicle
Genetic constraint (gnomAD): Loss-of-function variants: 23 observed, 32.8 expected, observed/expected ratio (o/e) 0.7, 90% interval 0.5 to 0.99. The upper end of that interval is the gene's LOEUF score, 0.99, which puts it in group 4 of 6, group 1 being the genes least tolerant of losing a copy. Missense variants: 393 observed, 408.07 expected, observed/expected ratio (o/e) 0.96, 90% interval 0.89 to 1.05. Synonymous variants: 130 observed, 141.45 expected, observed/expected ratio (o/e) 0.92, 90% interval 0.8 to 1.06.
Homologues: Orthologues: chimpanzee SNX7 (99% identical), macaque SNX7 (98% identical), dog SNX7 (92% identical), pig SNX7 (92% identical), guinea pig SNX7 (90% identical), rabbit SNX7 (90% identical), rat Snx7 (89% identical), mouse Snx7 (89% identical), tropical clawed frog snx7 (65% identical), zebrafish snx7 (57% identical). Paralogues in human: SNX30 (43% identical), SNX18 (22% identical), SNX1 (20% identical), SNX2 (20% identical), SNX9 (19% identical), SNX4 (19% identical), SNX33 (18% identical), SNX5 (16% identical), SNX6 (15% identical), SNX32 (15% identical), SNX8 (14% identical), SNX12 (10% identical), and 3 more.
Diseases named in the same sentence as SNX7 in open-access papers:
SNX7 is named in the same sentence as 13 diseases in open-access papers, as found by Europe PMC text mining. Sharing a sentence is not in itself a finding about the gene and the disease. The quoted sentences say what the papers report.
lung adenocarcinoma (2 papers, 2023 to 2025). A carcinoma that arises from the lung and is characterized by the presence of malignant glandular epithelial cells. "Another study identified SNX7 as an unfavorable prognosis gene in lung adenocarcinoma." (PMID 37743471, 2023). "For instance, one study developed a predictive model for recurrence in early-stage lung adenocarcinoma, incorporating SNX7 alongside other epithelial-to-mesenchymal transition-related genes (AGL, ECM1, ENPP1, SNX7, and TSPAN12)." (PMID 37743471, 2023).
Alzheimer disease (1 paper, 2020). A progressive, neurodegenerative disease characterized by loss of function and death of nerve cells in several areas of the brain leading to loss of cognitive function such as memory and language. "Snx7 has been related to Alzheimer’s disease pathogenesis through the reduction of amyloid-beta expression." (PMID 32093602, 2020).
bladder cancer (1 paper, 2023). "In addition, SNX7 may also be involved in tumorigenesis and development of small cell lung cancer and bladder cancer." (PMID 37743471, 2023).
cervical cancer (1 paper, 2025). A primary or metastatic malignant neoplasm involving the cervix. "This study revealed MPP5, SNX7, LSM12, and GALNT3 as genes linked to the prognosis of cervical cancer patients receiving concurrent radiotherapy, through the analysis of the GEO database." (PMID 41171827, 2025). "The prognostic risk model constructed in this study, based on the four genes MPP5, SNX7, LSM12, and GALNT3, demonstrated promising predictive performance for radiotherapy outcomes in cervical cancer patients, particularly in the medium- to long-term follow-up, with an AUC of 0.75 at 3 years." (PMID 41171827, 2025).
Cognitive impairment (1 paper, 2020). Abnormal cognition is characterized by deficits in thinking, reasoning, or remembering. "In addition, Snx7 may participate in the control of glutamatergic and dopaminergic neurotransmission via the regulation of the kynurenine pathway, which is related to psychotic symptoms and cognitive impairment." (PMID 32093602, 2020).
hepatocellular carcinoma (1 paper, 2023). A malignant tumor that arises from hepatocytes. "Secondly, the exact molecular mechanism underlying the involvement of SNX7 in hepatocellular carcinoma remains unclear and requires further investigation in future studies." (PMID 37743471, 2023).
liver cancer (1 paper, 2023). An epithelial or non-epithelial malignant neoplasm that arises from the liver. "First of all, we analyzed the capacity of SNX7 in the separation of liver cancer from normal samples based on the GSE144269, GSE45267, GSE112790 and GSE14520 datasets." (PMID 37743471, 2023).
liver cirrhosis (1 paper, 2023). "Furthermore, we found significantly higher SNX7 mRNA levels in HCC compared to liver cirrhosis samples (p < 0.001)." (PMID 37743471, 2023).
lung carcinoma (1 paper, 2025). "Recent studies indicate that the atypical expression of SNX7 may hold clinical significance in forecasting the advancement of lung cancer." (PMID 41171827, 2025).
Stroke (1 paper, 2020). Sudden impairment of blood flow to a part of the brain due to occlusion or rupture of an artery to the brain. "Exosomes harvested from Mir133b (paired with C87436, alpha-1,2-mannosyltransferase Alg9 and sorting nexin Snx7) overexpressing mesenchymal stem cells may improve neural plasticity and functional recovery after stroke in the rat brain." (PMID 32093602, 2020).
tumor (3 papers, 2023 to 2025). "Taken together, our study presents important insights into the potential role of SNX7 as a tumor biomarker in HCC." (PMID 37743471, 2023). "Immunohistochemistry (IHC) on clinical tumor samples confirmed that the protein expression levels of MPP5, SNX7, LSM12, and GALNT3 were distinctively predictive for CC patients." (PMID 41171827, 2025). "However, from a prognostic perspective, CD5, SLCO1B1, and CD79A have been demonstrated to have protective value in various tumors, whereas ETV5, FZD7, SNX7, and SLC1A7 are involved in tumor progression." (PMID 37680641, 2023).
neurodegenerative disease (1 paper, 2023). A disorder of the central nervous system characterized by gradual and progressive loss of neural tissue and neurologic function. "Therefore, the increased SNX7 expression observed throughout disease stages supports previous findings suggesting a role of the intracellular endosomal trafficking in PD and other neurodegenerative diseases." (PMID 37347276, 2023).
SNX7 also shares sentences with these, for which no sentence is quoted: small cell lung carcinoma (1 paper).